VN1R4 (vomeronasal 1 receptor 4)
Description:
Putative pheromone receptor.
Synonyms: V1RL4
Tractability: Antibody: UniProt places it where antibodies can reach, with medium confidence; UniProt predicts a signal peptide or a membrane-spanning region; its Gene Ontology location is reachable by antibodies, with medium confidence.
Gene: Protein-coding gene on chromosome 19 (53,266,676 to 53,267,723, reverse strand). Ensembl gene ENSG00000228567.
Subcellular location: Cell membrane
Gene Ontology:
Molecular function: pheromone binding; pheromone receptor activity
Biological process: G protein-coupled receptor signaling pathway; sensory perception of chemical stimulus
Cellular component: plasma membrane; membrane
Genetic constraint (gnomAD): Loss-of-function variants: 0 observed, 0.55 expected, observed/expected ratio (o/e) 0, 90% interval 0 to 1.83. That is too few expected variants to judge how well the gene tolerates losing a copy. Missense variants: 291 observed, 359.33 expected, observed/expected ratio (o/e) 0.81, 90% interval 0.74 to 0.89. Synonymous variants: 97 observed, 133.91 expected, observed/expected ratio (o/e) 0.72, 90% interval 0.61 to 0.86.
Homologues: Orthologues: rabbit ORYCUNV1R1573 (53% identical), rabbit ORYCUNV1R1576 (53% identical), mouse Vmn1r237 (51% identical), mouse Vmn1r234 (49% identical), rat Vom1r-ps20 (47% identical), mouse Vmn1r236 (47% identical), rat Vom1r21 (47% identical), rat Vom1r22 (47% identical), mouse Vmn1r235 (46% identical), rat Vmn1r235 (45% identical), mouse Vmn1r233 (44% identical), rat Vom1r16 (44% identical), and 2 more. Paralogues in human: VN1R2 (56% identical), VN1R1 (44% identical), VN1R5 (27% identical).